RNU6-728P (RNA, U6 small nuclear 728, pseudogene)
Gene: Small nuclear RNA gene on chromosome 10 (122,345,690 to 122,345,793, forward strand). Ensembl gene ENSG00000202245.
Homologues: Orthologues: chimpanzee U6 (99% identical), macaque U6 (89% identical). Paralogues in human: RNU6-1152P (88% identical), RNU6-211P (88% identical), RNU6-21P (87% identical), RNU6-820P (87% identical), RNU6-144P (86% identical), RNU6-20P (86% identical), RNU6-310P (86% identical), RNU6-35P (86% identical), RNU6-457P (86% identical), RNU6-476P (86% identical), RNU6-641P (86% identical), RNU6-686P (86% identical), and 1284 more.